KL (klotho)
Diseases named in the same sentence as KL in open-access papers (continued):
Sharing a sentence is not in itself a finding about the gene and the disease.
osteosarcoma (1 paper, 2020). A usually aggressive malignant bone-forming mesenchymal neoplasm, predominantly affecting adolescents and young adults. "Firstly, we investigated whether klotho is associated with tumor growth of osteosarcoma." (PMID 32614356, 2020). "Lentivirus-mediated overexpression of klotho significantly decreased tumor volume and weight in osteosarcoma mice." (PMID 32614356, 2020). "PAS staining also showed that overexpression of klotho significantly decreased the production of glycogen in osteosarcoma." (PMID 32614356, 2020). "Determination of PCNA and Ki67 expression revealed that overexpression of klotho inhibited cell proliferation in tumor tissues obtained from osteosarcoma xenografts." (PMID 32614356, 2020). "Nevertheless, lentivirus-mediated overexpression of klotho obviously suppressed the TUNEL-positive cell number, suggesting that enhanced expression of klotho was associated with induction of apoptosis in osteosarcoma." (PMID 32614356, 2020). "Molecularly, IHC analysis of PCNA and Ki67 expression revealed that overexpression of klotho inhibited cell proliferation in tumor tissues obtained from osteosarcoma xenografts, supporting the anti-proliferative role of klotho in osteosarcoma." (PMID 32614356, 2020). "In conclusion, we have shown that elevated expression of klotho is able to suppress growth and pulmonary metastasis of osteosarcoma in vivo." (PMID 32614356, 2020). "In our study, we found that lentivirus-mediated overexpression of klotho significantly decreased tumor volume and weight in osteosarcoma mice." (PMID 32614356, 2020). "Therefore, the present study, for the first time, explored the effects of klotho in osteosarcoma proliferation and metastasis." (PMID 32614356, 2020). "The present study investigated the role of klotho on growth and metastasis of osteosarcoma cells." (PMID 32614356, 2020). "In our study, overexpression of klotho exhibited a significant anti-oncogenic role in osteosarcoma." (PMID 32614356, 2020). "Klotho overexpression in transduced osteosarcoma cells was confirmed by western blot." (PMID 32614356, 2020). "However, lentivirus-mediated overexpression of klotho significantly decreased tumor volume and weight in the mice model of osteosarcoma." (PMID 32614356, 2020). "Collectively, these data suggested the anti-proliferative role of klotho in osteosarcoma." (PMID 32614356, 2020). "Therefore, we evaluated the role of klotho in osteosarcoma metastasis in vivo." (PMID 32614356, 2020). "However, overexpression of klotho significantly decreased the PAS-positive cells per field and thus suppressed the production of glycogen in osteosarcoma." (PMID 32614356, 2020). "Then, PAS staining was used to assess the glycogen content of osteosarcoma with or without overexpressed klotho." (PMID 32614356, 2020). "In order to determine whether klotho was involved in tumor growth, mice were injected with osteosarcoma cells with or without overexpression of klotho, and tumor volume and weight were evaluated." (PMID 32614356, 2020). "However, the precise role of klotho is osteosarcoma has not been evaluated." (PMID 32614356, 2020). "However, the role of klotho in the pathogenesis of osteosarcoma has never been reported." (PMID 32614356, 2020).
Pancytopenia (1 paper, 2022). An abnormal reduction in numbers of all blood cell types (red blood cells, white blood cells, and platelets). "Meanwhile, irradiation-induced myelosuppression was exacerbated by the Klotho treatment, manifested by a smaller HSC pool, more HSC apoptosis, and more severe pancytopenia." (PMID 36014901, 2022).
parathyroid adenomas (1 paper, 2019). "Our results are consistent with previously published data, demonstrating decreased expression of Klotho mRNA and protein in parathyroid adenomas." (PMID 30832348, 2019). "As deletion of KL functions in parathyroid gland hyperplasia, this gene may also contribute to the development of parathyroid adenoma." (PMID 30832348, 2019). "The KL and PTH genes, which play significant roles in calcium regulation, were down-regulated in parathyroid adenoma compared with normal parathyroid tissue samples." (PMID 30832348, 2019).
parathyroid disease (1 paper, 2025). "Among these, several genes such as APC, CEP152, CREBBP, FAM111A, FGFR1, KL and MMP14 have been previously suggested to be associated with parathyroid disease." (PMID 40434298, 2025).
Peritoneal Fibrosis (1 paper, 2023). Disorder characterized by a wide range of structural changes in PERITONEUM, resulting from fibrogenic or inflammatory processes. "Most recently, Kadoya’s team reported that klotho protected the peritoneal membrane from peritoneal fibrosis in transgenic-PD mice through attenuation of the Wnt/β-catenin signaling pathway." (PMID 36724065, 2023). "In a PD model, the peritoneal membrane was protected from peritoneal fibrosis in klotho transgenic rats through attenuation of the Wnt/β-catenin signaling pathway, but the mechanism was not shown." (PMID 36724065, 2023). "To reveal whether EZH2 and klotho are involved in the pathogenesis of PD-related peritoneal fibrosis, we examined their expression in HPMCs treated with different concentrations of glucose for 48 h." (PMID 36724065, 2023). "However the detailed mechanism of EZH2 and klotho in peritoneal fibrosis remained unclear." (PMID 36724065, 2023). "Therefore, this raises the question of whether klotho participates in peritoneal fibrosis by regulating lipid metabolism." (PMID 36724065, 2023). "Therefore we speculated that klotho was involved in peritoneal fibrosis possibly mediated by regulating lipid metabolism." (PMID 36724065, 2023). "Combining these findings, we found that EZH2 regulated lipid deposition, peritoneal fibrosis, and EMT mediated by klotho." (PMID 36724065, 2023). "Hence, EZH2 and klotho could act as potential targets for the treatment of peritoneal fibrosis." (PMID 36724065, 2023). "In vivo experiments also revealed that GSK343 could relieve peritoneal fibrosis, lipid deposition and EMT by mitigating EZH2 and restoring klotho expression." (PMID 36724065, 2023).
primary aldosteronism (1 paper, 2024). An endocrine disorder characterized by excessive production of aldosterone by the adrenal glands. "The interplay between Klotho and adrenal steroidogenesis has been under investigation, given its potential implications for pathophysiological states such as primary aldosteronism." (PMID 38573585, 2024).
retinal degeneration (1 paper, 2025). Degeneration of the retina. "The results revealed that Klotho null mutation leads to retinal degeneration characterized by functional impairments, gliosis, and amyloid-beta and hyperphosphorylated tau protein deposition in the retina." (PMID 40373038, 2025). "We have identified characteristics of retinal degeneration induced by Klotho null mutation including retinal function impairment, aggregation of Aβ and pTau, and the glia cell activation, which were observed in AD patients but had not been reported with Klotho null mutation." (PMID 40373038, 2025).
retinal disease (1 paper, 2024). "Excessive klotho expression has been observed in states of retinal disease, suggesting that systemic P toxicity could be a contributing factor." (PMID 38904033, 2024).
Right ventricular hypertrophy (1 paper, 2020). In this case the right ventricle is more muscular than normal, causing a characteristic boot-shaped (coeur-en-sabot) appearance as seen on anterior- posterior chest x-rays. "Additionally, while PL-treated rats exposed to neonatal hyperoxia had increased RV/LV + S, the degree of right ventricular hypertrophy significantly improved following early administration of Klotho." (PMID 32704023, 2020).
sarcoma (1 paper, 2016). A usually aggressive malignant neoplasm of the soft tissue or bone. "In this study, we have observed that the atrophic muscles in sarcoma-bearing mice feature the upregulated expression of both Notch genes and TNF-α, while the expression of anti-inflammation factor Klotho was downregulated." (PMID 27378829, 2016).
seminoma (1 paper, 2025). A radiosensitive malignant germ cell tumor found in the testis (especially undescended), and extragonadal sites (anterior mediastinum and pineal gland). "IHC confirmed the marked expression of FGF23 solely in OCT4-positive GCNIS cells that also expressed FGFR1, while Klotho was exclusively expressed in normal germ cells and not found in any of the OCT4-positive cancer cells including seminoma and EC." (PMID 40279260, 2025).
sleep disorder (1 paper, 2021). A change from the patient's baseline sleeping pattern, in the hours slept and/or an alteration/dysfunction in the stages of sleep. "Additionally, recent evidence suggests that sleep deprivation and sleep disorders may lead to decreased concentrations of the circulating anti‐aging protein Klotho, which is a tumor suppressor and modulator of insulin‐like growth factor‐1 and other oncogenic signaling pathways." (PMID 32895918, 2021).
squamous cell carcinoma (1 paper, 2022). A carcinoma arising from squamous epithelial cells. "Interestingly, these subtypes are enriched in STK11/LKB1 mutations (subtype 4) and squamous cell carcinomas (subtype 6), which are both features of the KL model." (PMID 35941104, 2022).
Thrombocytopenia (1 paper, 2024). A reduction in the number of circulating thrombocytes. "Interestingly, Klotho concentrations above 1068 mg/dL at two hours were associated with a 98.9% lower risk of thrombocytopenia 72 h following CPB." (PMID 38786957, 2024).
thyroid tumor (1 paper, 2024). A benign or malignant neoplasm affecting the thyroid gland. "New studies have found that klotho protein is associated with the development of thyroid tumours." (PMID 38696398, 2024).
Tinnitus (1 paper, 2025). Tinnitus is an auditory perception that can be described as the experience of sound, in the ear or in the head, in the absence of external acoustic stimulation. "Multivariable logistic regression uncovered consistent inverse associations between serum Klotho levels and tinnitus incidence across progressively adjusted models (ORs: 0.68–0.70, p = 0.009–0.01)." (PMID 40737282, 2025). "Subgroup and interaction analyses evaluated potential effect modification in the serum Klotho-tinnitus association across various relevant subgroups." (PMID 40737282, 2025). "Serum Klotho concentrations showed a consistent inverse association with tinnitus prevalence in US adults, with the strongest effect observed in individuals aged 50–69 years." (PMID 40737282, 2025). "Taken together, high serum Klotho levels are associated with reduced tinnitus prevalence in adults aged 50–59 years, with suggestive evidence in those aged 60–69." (PMID 40737282, 2025). "In this study, we employed a cross-sectional design to investigate the association between serum Klotho protein levels and tinnitus in a cohort of middle-aged and elderly individuals from National Health and Nutrition Examination Survey (NHANES)." (PMID 40737282, 2025). "The aim of this study was to investigate the associations between serum Klotho levels and tinnitus focusing on prevalence, duration and severity in middle-aged and older adults." (PMID 40737282, 2025). "Stratified analyses revealed significant age-dependent associations between serum Klotho levels and tinnitus prevalence." (PMID 40737282, 2025). "Similarly, inverse associations between serum Klotho concentrations and tinnitus prevalence were observed consistently across both continuous and categorical variable analyses." (PMID 40737282, 2025). "A potential association was found between Klotho and tinnitus duration (p = 0.058)." (PMID 40737282, 2025). "In adults aged 50−59 years, high Klotho levels (vs. low) were associated with a 45% reduction in tinnitus risk in the unadjusted model (OR=0.55, 95% CI: 0.31–0.97, p = 0.038), with a similar trend in the fully adjusted model (OR=0.55, 95% CI: 0.31–0.99, p = 0.046)." (PMID 40737282, 2025). "However, the relationship between serum Klotho levels and tinnitus risk remains poorly characterized." (PMID 40737282, 2025). "Association between serum Klotho and tinnitus stratified by age." (PMID 40737282, 2025). "However, the association between serum Klotho levels and tinnitus remains unexplored." (PMID 40737282, 2025). "Significantly, a potential inverse relationship was also uncovered between Klotho and the duration of tinnitus." (PMID 40737282, 2025). "This study utilized data from the three cycles of NHANES (2009–2012 and 2015–2016), focusing on participants aged 40–79 years, to examine the correlation between serum Klotho concentrations and tinnitus prevalence as well as the duration and severity." (PMID 40737282, 2025). "As an anti-aging protein, although studies increasingly suggest that the Klotho plays a role in the auditory system, the link between serum Klotho levels and tinnitus remains poorly characterized." (PMID 40737282, 2025). "Univariable and multivariable logistic regression was used to evaluate the relationship between serum Klotho levels and tinnitus, with adjustment for potential confounders and further age-stratified analyses." (PMID 40737282, 2025). "The finding suggests a possible link between serum Klotho levels and tinnitus duration, which warrants further investigation, despite potential limitations due to our sample size." (PMID 40737282, 2025). "The complete-case analysis, following exclusion of missing values for serum Klotho, tinnitus, and covariates, included 3,280 eligible participants." (PMID 40737282, 2025). "We also observed that participants with high levels of serum Klotho were significantly less likely to report tinnitus than those with low levels of serum Klotho." (PMID 40737282, 2025).
Tinnitus (continued). "In conclusion, our research seeks to contribute valuable knowledge to the field of otology and geriatrics, and the epidemiological evidence on the role of Klotho in tinnitus." (PMID 40737282, 2025). "Our findings suggested that higher serum Klotho concentrations may protect against tinnitus in middle-aged adults (50–69 years), with the strongest effect observed in the 50–59 age group." (PMID 40737282, 2025). "Therefore, exploring the correlation between serum Klotho and tinnitus phenotypes presents a promising avenue for advancing our understanding of tinnitus’ etiology and potential interventions." (PMID 40737282, 2025). "Therefore, targeted modulation of Klotho expression represents a promising therapeutic strategy for tinnitus prevention and treatment." (PMID 40737282, 2025). "Our findings demonstrate the relationship between serum Klotho levels and tinnitus prevalence, suggesting that targeted manipulation of circulating Klotho may represent a viable therapeutic strategy." (PMID 40737282, 2025). "Consequently, these associations remained significant and robust in 50–59 age group after adjusting for confounders and other covariates, suggesting that Klotho may exert independent effects on the prevalence of tinnitus." (PMID 40737282, 2025). "Additionally, restricted cubic spline analysis revealed a linear inverse association between Klotho and tinnitus risk stratified by age (all p for nonlinear >0.15)." (PMID 40737282, 2025). "The potential of Klotho-level modulation may serve as a future research direction in tinnitus." (PMID 40737282, 2025). "We hypothesize distinct mechanistic roles of Klotho in the prevalence and duration of tinnitus." (PMID 40737282, 2025). "Furthermore, restricted cubic spline was utilized to further analysis the nonlinear association between Serum Klotho and tinnitus risk (all p for nonlinear >0.15)." (PMID 40737282, 2025). "Conversely, the non-Hispanic black, the other Hispanic, PIR and serum Klotho were significantly and negatively correlated with tinnitus." (PMID 40737282, 2025). "Our findings uniquely uncovered the significant negative correlation between serum Klotho levels and tinnitus prevalence in a human population, complementing animal studies that suggested a neuroprotective role of Klotho proteins in auditory pathways." (PMID 40737282, 2025). "In analyzing tinnitus duration, we found that the non-chronic tinnitus group had a higher proportion of elevated Klotho levels, while the chronic tinnitus group had a greater prevalence of reduced Klotho levels, suggesting a potential inverse relationship." (PMID 40737282, 2025).
triple-negative breast carcinoma (1 paper, 2025). An invasive breast carcinoma which is negative for expression of estrogen receptor (ER), progesterone receptor (PR), and human epidermal growth factor receptor 2 (HER2). "In TNBC (Triple-Negative Breast Cancer), Klotho is overexpressed in a subset of TNBC cells and is necessary for cell survival." (PMID 40004457, 2025).
type 2 diabetic nephropathy (1 paper, 2021). "Consistent with our previous study demonstrating that soluble klotho was negatively correlated with albuminuria in type 2 diabetic nephropathy, soluble klotho in culture media was decreased by palmitate treatment compared to control." (PMID 33891667, 2021).
vestibular disorder (1 paper, 2025). Pathological processes of the vestibular labyrinth which contains part of the balancing apparatus. "Additionally, Klotho downregulation decreases transient receptor potential vanilloid 5(TRPV5) and TRPV6 levels, altering inner ear Ca2+ regulation and causing sensory cell transduction defects that manifest as auditory or vestibular disorders." (PMID 40737282, 2025).